PRL (prolactin)
Diseases named in the same sentence as PRL in open-access papers (continued):
Sharing a sentence is not in itself a finding about the gene and the disease.
tumor (continued). "In addition, PRL biological action may vary depending on the hormonal environment, especially given our recent observation that PRL effectively counteracts progestin-induction of the tumor-initiating CK5-positive cell population." (PMID 23758962, 2013). "The lactotrope cell lines include 235-1, derived from a rat tumor; MMQ, also from a rat tumor; whereas the GH3 cell line, derived from another rat tumor, may be considered both a lactotrope and somatotrope (somatolactotrope) due to its expression of both prolactin and growth hormone." (PMID 22132145, 2011). "Moreover, our results show that PRL may be a better tumour marker than CEA in patients with colorectal malignancy." (PMID 15617576, 2004). "Prolactin may be a better tumour marker than CEA in patients with colorectal malignancy." (PMID 15617576, 2004). "Experimental evidence supports the mitogenic role of PRL, as PRL-overexpressing MDA-MB-435 cells exhibit increased proliferation, tumor growth, migration, and metastasis." (PMID 41370498, 2025). "Analysis of multiple human cancers reveals distinct expression patterns of cyclooxygenase-2 (COX-2), prolactin, and PRLR in tumor and stromal cells." (PMID 41583437, 2025). "Subsequent experiments uncover a key intercellular pathway: elevated COX-2 levels in tumor cells promoted prostaglandin E2 (PGE2 synthesis, which upregulates nuclear receptor 4A (NR4A) in stromal cells, stimulating prolactin secretion." (PMID 41583437, 2025). "Cabergoline is the preferred first-line dopamine agonist for prolactinoma compared to bromocriptine (BRC), effectively lowering prolactin (PRL) levels and reducing tumor size." (PMID 40236612, 2025). "Only PRL-secreting PitNETs showed a significant correlation between VEGF protein levels, PRL expression, and MIB1 LI-positive tumor cells." (PMID 41614857, 2025). "Collectively, the inhibition of expression of growth factors such as PRL, PDGF, HTR1B, and VEGF in fibroid xenografts provides another mechanism for reducing tumor cell proliferation and angiogenesis in fibroids." (PMID 38994944, 2024). "At diagnosis, the median tumor diameter was 6 mm (IQR 5–9 mm), and the median PRL was 112.3 ng/ml (IQR 50–149.7 ng/ml)." (PMID 38499816, 2024). "Prolactin signaling via Janus kinase-signal transducer and activator of transcription (JAK-STAT) is shown to promote tumor growth and the Hippo pathway regulates metabolic reprogramming to promote the growth of malignant tumors." (PMID 38982514, 2024). "Immunohistochemically, the tumor cells were diffusely positive for PIT1 and also focally positive for TSH, GH, and PRL." (PMID 39816322, 2024). "Thus, PRL may stimulate tumour angiogenesis via autocrine, paracrine, and endocrine pathways." (PMID 39663784, 2024). "Immunohistochemically, the tumor cells were diffusely positive for PIT1 and focally positive for thyroid-stimulating hormone, growth hormone, and prolactin." (PMID 39816322, 2024). "Histochemistry analysis of the tumor revealed positive staining for TSH, growth hormone (GH), prolactin (PRL), luteinizing hormone (LH), and somatostatin receptor 2 (SSTR2)." (PMID 38516415, 2024). "According to miRNomics, these tumours were classified into four groups based on microRNA (miRNA) clusters as prolactin-secreting (miR-1), growth hormone (miR-2), ACTH (miR-3) and follicle-stimulating hormone/ luteinising hormone tumours (miR-4)." (PMID 38187082, 2023). "Some authors have described that TGF-β is elevated in aggressive PRL-secreting tumors, both locally and in the serum (and serum TGF-β is directly correlated with tumor dimensions and aggressivity)." (PMID 37958702, 2023).
tumor (continued). "Blocking ATX activity changed the phenotype of the mice by decreasing the plasma concentrations of CXCL9, CXCL10, and CCl2 and the tumor concentrations of LIF, TGFβ1, TGFβ2, and prolactin." (PMID 37296899, 2023). "In concordance with previous studies demonstrating the role of 16kD PRL in reducing B16-F10, HCT116, and PC-3 tumor cell growth in vivo, we have shown that 14 kDa hGH significantly reduces primary tumor growth and metastasis in C57BL/6 mice." (PMID 37240223, 2023). "COL4A1 manages the inhibition of cell death; the activation of focal adhesion kinase; the cell cycle; tumor angiogenesis; the PI3K/MAPK, PI3K/AKT, and PRL/PAK1 signaling pathways, and the discoidin domain receptor (DDR) axes." (PMID 38004422, 2023). "GH3 xenograft tumor-bearing mice showed a growth hormone-oversecretion phenotype as evidenced by increased plasma GH and PRL (note that GH3 cells also produce PRL), increased body weight and enlarging organs (e.g., the liver and spleen)." (PMID 37215573, 2023). "In this tumor, both DRD2 agonists were effective in reducing PRL secretion in the cell culture media (cabergoline: −46.14 ± 1.2%; UNC9994: −33.7 ± 0.57%; both p < 0.001 vs. bas)." (PMID 37370829, 2023). "However, there are still advantages to incomplete surgical resection, including rapid decompression of the optic chiasm to restore vision, treatment of CSF leak or tumoral apoplexy, and reduction of tumor burden, which may allow for prolactin normalization at similar DA doses." (PMID 37143698, 2023). "Histology confirmed the presence of a lactotroph macroadenoma that was sparsely granulated and the tumor cells were strongly positive for PIT-1 and PRL." (PMID 36927797, 2023). "At the last follow-up [median 9 years (interquartile range (IQR) 4-15)], the median PRL was 12 μg/L (IQR 4-126), and the median tumor diameter was 22 mm (IQR 3-40)." (PMID 37403202, 2023). "Thus, if a reduction in PRL or tumor size has not been obtained 1 year after initiation of DA treatment, a further decrease in PRL and/or tumor size may be protracted and/or insufficient, and in these patients a more thorough follow-up or multimodal treatment is warranted." (PMID 37403202, 2023). "The similarity between prolactin and growth hormones and its influence on the JAK/STAT signaling pathway strongly indicate its impact on tumor invasiveness." (PMID 35625802, 2022). "It is also important to note that in this study we focused on the relation between prolactin and RNFL thickness at the time of diagnosis–an approach that is agnostic to treatment type (e.g. open vs trans-sphenoidal tumor resection or medical therapy)." (PMID 35921360, 2022). "The patients were categorized by tumor type: ACTH secreting (n = 2), GH secreting (n = 6), PRL secreting (n = 4), NF PitNETs (n = 22)." (PMID 36158656, 2022). "Moreover, inline with the differentiation role of PRL in the breast, expression of PRL mRNA was associated with more differentiated tumors, early stage, smaller tumor size and absence of distant metastasis with higher PRL mRNA levels correlating with prolonged relapse free survival." (PMID 36157462, 2022). "In contrast, Shemanko and her colleagues found that higher tumor PRLR protein levels correlated with a shorter time to bone metastasis, consistent with experimental PRL-induced osteoclast differentiation." (PMID 35784527, 2022). "SOCS5, another common DEG identified in PRL signalling, is a member of the suppressor of cytokine signalling (SOCS) protein family with controversial tumour-promoting and tumour-suppressive roles in cancer." (PMID 35773139, 2022). "For instance, in prolactin tumors, BMP4 facilitates the expression of proliferation-related genes such as C-MYC to provoke tumor cell proliferation." (PMID 35401213, 2022).
tumor (continued). "The downregulated miR-200c has been previously reported to be upregulated in PRL secreting PitNET tumor cell line (MMQ) and inhibits the apoptosis of tumor cells by targeting PTEN/Akt pathway confirming its tumor promoting role in PitNETs." (PMID 36158656, 2022). "Other PitNET-expressing PRL includes the Mammosomatotroph tumor, the Mature plurihormonal PIT1-lineage, the Immature PIT1-lineage tumor, and the Acidophil stem cell tumor and Mixed somatotroph and lactotroph tumor." (PMID 36714572, 2022). "Immunocytochemical staining showed that this TSH PitNET was a plurihormonal tumor of Pit-1 lineage producing TSH, GH, and PRL." (PMID 36539773, 2022). "EGFR, ErbB2, and ErbB3 are all endogenously expressed in rat lacto-somatotroph tumor cells, and in vitro treatment with EGFR TKIs was shown to prevent PRL secretion." (PMID 34867776, 2021). "The MRI demonstrated a rapid enlargement of the tumor with suprasellar extension and encasing the right ICA, and the serum prolactin increased to 339.0 ng/mL again." (PMID 34715828, 2021). "As a common PRL and oestradiol (E2) pathway, PAK1 cooperates with ER to stimulate tumour cell metastasis, inducing tamoxifen resistance." (PMID 34651424, 2021). "Second, this study combined protein microarray analysis to look for differentially expressed genes and found a significant correlation between PRL/PRLR and fibrosis in tumor tissues." (PMID 34539753, 2021). "The correlation between gender and baseline PRL was independent of the age at diagnosis, indicating that the high prevalence of large tumours in men is not caused by a delay in diagnosis, but by a higher frequency of rapidly growing tumours in this group of patients." (PMID 33963239, 2021). "The combination of everolimus and cabergoline was shown to inhibit mammosomatrotroph tumor GH3 cell proliferation and prolactin levels in vitro." (PMID 32012988, 2020). "Distinct tumor type-specific profiles were shown in earlier studies as well: GT-PTs, ACTH-PTs, GH-PTs, PRL-PTs and NFPTs." (PMID 32201880, 2020). "Co-incubation of pituitary lactotroph tumor slices with the anti-EM66 and PRL antisera showed that some EM66-positive cells were lactotrophs." (PMID 30853937, 2019). "Increased collagen I deposition in TME makes tumor ECM stiff, stimulating tumor growth by modulating a set of signaling events, such as shifting the balance from prolactin signaling (JAK2/STAT5) toward tumor progression signaling (ERK)." (PMID 30220913, 2018). "Patients with GH/PRL-secreting adenomas showed 50% IGF-I normalization, and tumor shrinkage was observed in 13 of 21 patients with macroadenomas." (PMID 30186234, 2018). "Plasma PK at 2 hours post-dose was 2.6 ug/mL, serum prolactin induction was observed as a surrogate marker of target engagement, and DRD2 was expressed in all evaluated archival tumor specimens." (PMID 29108308, 2017). "Cabergoline (CAB) has been largely recommended as the first line agent, due to its better tolerability and higher efficacy in normalizing prolactin (PRL) levels and inducing tumor shrinkage, compared to bromocriptine." (PMID 25699020, 2015). "Elevated serum prolactin has been shown to correlate with CRC malignancy and is observed in many CRC cell lines and tumour specimens." (PMID 25987887, 2015). "Beside the already mentioned pro-proliferative activity of PRLR in diverse tumor entities, several groups have reported about a PRLR/PRL-mediated inhibition of apoptosis especially in response to chemotherapy." (PMID 24257371, 2013). "In this study we have examined PRL, TNF alpha and NO levels in plasma and in tumour homogenates during goserelin administration and, similar behaviour was observed." (PMID 18045456, 2007). "In plasma the mean value of PRL levels was lower in healthy controls [C] (28.5 ± 0.1 ng/ml, n = 20) than in rats with NMU tumours [T] (51.3 ± 2.2 ng/ml, n = 20), P < 0.01." (PMID 18045456, 2007).
tumor (continued). "More rarely, treatment responses are discordant, with volume increase despite a marked drop in prolactin levels or tumor shrinkage without declining prolactin levels." (PMID 41017446, 2026). "The other studies required prolactin normalization with “stable neuroimaging” during DA treatment or with >50% tumor reduction without specifying DA treatment status." (PMID 41017446, 2026). "In DA resistant patients from which both data on tumor shrinkage and PRL levels were available (n = 18), DA treatment resulted in normalization of PRL levels in 7 (39%), despite a lack of tumor shrinkage by more than 30%." (PMID 41184667, 2025). "Our primary outcome was the concordance between IPSS-predicted lateralization (with and without PRL correction) and the actual tumor location confirmed intraoperatively and histopathologically." (PMID 41287677, 2025). "Excessive prolactin secretion typically leads to hypogonadotropic hypogonadism in up to 90% of cases, irrespective of tumor size." (PMID 40035956, 2025). "While no predictors of tumor shrinkage > 50% has been found, a predictor of PRL normalization has been identified." (PMID 40995599, 2025). "In depth analysis enabled us to separate the tumor clusters into GH1 and PRL expressing cells, the immune cells into CD4 T cells, CD8 T cells and monocytes (with subcategories, cf. Immune cell analysis) and structural cells into stem cells, pericytes, fibroblasts and endothelial cells." (PMID 40523964, 2025). "Nevertheless, neither tumor invasiveness nor gender predicted tumor shrinkage, which was more likely to occur in cases of PRL normalization." (PMID 40995599, 2025). "In select cases (i.e. normal prolactin and no visible tumour on MRI), withdrawal of DA after two or more years of therapy can be attempted with observed remission rates of 26 to 69%." (PMID 40004619, 2025). "DAs can reduce prolactin (PRL) synthesis and secretion and induce tumor shrinkage." (PMID 41184667, 2025). "This MIB1 LI-mediated reciprocal tumor stroma contact is unique to PRL-secreting and non-functioning PitNETs." (PMID 41614857, 2025). "Our data compliment their experimental findings as they relate to human tissue specimens and they provide evidence of the mutual correlation between the proliferative status of tumor and endothelial cells in PRL-secreting and non-functioning PitNETs." (PMID 41614857, 2025). "Comparison of baseline and 12-month results was further stratified in the treatment group by tumor type (non-functioning and PRL)." (PMID 41480366, 2025). "Tumor–endothelial cell proliferative interaction is specific to PRL-secreting and non-functioning PitNETs." (PMID 41614857, 2025). "When prolactin levels do not show significant decline with adherent dopamine agonist treatment, or when tumor size does not reduce sufficiently, alternative diagnoses should be entertained." (PMID 40255723, 2025). "Differences between PRL and NFPAs were more evident in treated NFPA patients <60 years, suggesting tumor type and age may influence biomarker sensitivity." (PMID 41480366, 2025). "It is based on the proportionality of prolactin levels and tumor mass in prolactinomas, which is not linear in NFPAs." (PMID 40960781, 2025). "Accordingly, tumours with POU class 1 homeobox 1 (Pit-1)-positivity with IHC staining for growth hormone (GH), prolactin (PRL), or thyroid stimulating hormone (TSH) were classified as somatotroph tumours, lactrotroph tumours, or thyrotroph tumours, respectively." (PMID 38756997, 2024). "Patients who did not experience remission had a higher increase in PRL levels for each rise in preoperative tumor volume than those who achieved remission." (PMID 38375408, 2024). "Particular attention should be directed to patients who demonstrate a significant decrease in PRL levels with no corresponding decrease in tumor diameter." (PMID 38370355, 2024).
tumor (continued). "An ongoing dilemma concerns the classification and clinical implications of patients with persistently marginally elevated prolactin levels after surgery, without symptoms or radiological tumor remnants." (PMID 39292628, 2024). "Experienced physicians dealing with large PSPA also know that tumor control takes priority over biochemical normalization, and, in numerous cases, prolactin levels never completely normalize despite extensive tumor shrinkage." (PMID 39109291, 2024). "All these patients displayed normal prolactin (PRL) levels without visible tumor remnants on MRI scan, 18, 34, and 36 years following their diagnosis." (PMID 39439563, 2024). "This was a tumour that was negative for all transcription factors but expressed positive prolactin, TSH and growth hormone." (PMID 38483762, 2024). "Although sufficient tumor shrinkage was not achieved, the PRL value was reduced, suggesting that the added therapeutic effects, such as tissue changes due to partial cabergoline, enabled functional total resection." (PMID 38516477, 2024). "This immune gene signature segregates along each tumor lineage and the transcription factor that determines their terminal differentiation: POU1F1-dependent GH-, TSH-, PRL-secreting PitNET; NR5A-1-driven gonadotrophinomas; and TBX19-dependent ACTH-secreting PitNET." (PMID 38790160, 2024). "Following immediate surgical treatment, the prolactin levels of the patient rapidly normalized, and the tumor-related delayed puberty resolved without any adverse events." (PMID 39202626, 2024). "Two tumours were immunoreactive for prolactin (with the report stating entirely negative for ACTH) and these patients achieved postoperative remission without further therapeutic interventions." (PMID 38889004, 2024). "Likewise, G129R, a PRL mimics that competes with PRL for binding PRLR, effectively antagonizes PRL but demonstrates limited anti-tumor effects." (PMID 38898487, 2024). "Prolactinomas are considered resistant to medical therapy when prolactin levels fail to normalize and tumor size is not reduced by 50%." (PMID 36950000, 2023). "PRL levels, maximum tumor diameters at diagnosis, and multimodal treatment did not predict combined response at the last follow-up." (PMID 37403202, 2023). "Postoperative maximal tumor diameter correlated with Knosp grade (p = 0.02); CAM 5.2 pattern (densely/sparsely granulated/mixed densely and sparsely granulated) was correlated with postoperative PRL level (p = 0.002), and with ki-67 (p < 0.001)." (PMID 38003353, 2023). "Initially, pazopanib demonstrated effectiveness in controlling tumor progression, reducing prolactin secretion, and providing a six-month period without disease progression." (PMID 37529607, 2023). "In 61 patients treated with DA monotherapy, the median serum PRL level decreased from 6274 μg/L (IQR 4013-11 557) at diagnosis to 8 μg/L (IQR 4–52) at the last follow-up (P < .001) and the median maximum tumor diameter decreased from 45 mm (IQR 41-52) to 16 mm (IQR 2-37) (P < .001)." (PMID 37403202, 2023). "In 14 patients, this was due to a lack of effect on PRL and/or tumor size, and in 4 patients, it was due to CSF leakage during DA treatment." (PMID 37403202, 2023). "On account of the incomplete differentiation of immature PIT-1-lineage tumor, there are monomorphic tumor cells with focal/variable staining for no hormones, or one or more of GH, PRL, β-TSH, and/or α-subunit in the tumor." (PMID 37324275, 2023). "Among the 15 NFPitNETs, immunohistochemistry (IHQ) was positive for ACTH in 7 cases, for GH in 3 cases, for prolactin in one case, for gonadotrophins in one case, and 3 tumours were negative for all pituitary hormones." (PMID 37720528, 2023). "Our patient was recommended for surgical resection after high doses of CAB failed to normalize his PRL and reduce tumor volume." (PMID 36927797, 2023).